MAS1 (MAS1 proto-oncogene, G protein-coupled receptor)
Diseases named in the same sentence as MAS1 in open-access papers:
MAS1 is named in the same sentence as 69 diseases in open-access papers, as found by Europe PMC text mining. Sharing a sentence is not in itself a finding about the gene and the disease. The quoted sentences say what the papers report.
COVID-19 (10 papers, 2021 to 2025). A disease caused by infection with severe acute respiratory syndrome coronavirus 2. "Higher expression of MAS-1 (MAS-1high) likely tracked IFhigh, as this signature comprised IF-related genes (e.g., C5AR1, MYD88) and higher baseline expression of MAS-1 associated with higherall-cause mortality hazards during acute COVID-19 as well as in the FHS." (PMID 37311745, 2023). "Congruently, we found that the baseline IHG status and SAS-1/MAS-1 profiles showed similar prognostication during acute COVID-19." (PMID 37311745, 2023). "It is proposed that RAS balance could be restored in COVID-19 patients through Mas1 activation downstream of ACE2 activity, with 20E (BIO101), a non-peptidic Mas receptor (Mas1) activator developed by Biophytis." (PMID 33947076, 2021). "In sum, concerning the treatment of COVID-19 with LOS, ACE2 expression is associated with MAS1." (PMID 34937861, 2021). "Classical AAbs targeting Angiotensin II (AngII), Angiotensin Converting Enzyme 2 (ACE2) and MAS1 oncogene (MAS) receptors were frequently observed in COVID-19 patients, suggesting that the production of GPCR-fAAb may begin even at the time of acute COVID-19 infection." (PMID 40724994, 2025). "MAS1 expression could predict the COVID-19 treatment response of LOS." (PMID 34937861, 2021). "In this context, autoantibodies such as ACE2-aab, AGTR2-aab, BDKRB1-aab, CXCR3-aab, MAS1-aab, CHRM5-aab, NRP1-aab, F2R-aab, STAB1-aab appeared to play a major role in stratifying COVID-19 by disease burden." (PMID 35264564, 2022). "Thus, MAS1 expression could predict the COVID-19 treatment response of LOS." (PMID 34937861, 2021). "We do not think that differences in the healthy control groups play a role as we did not observe different AAB levels, except for MAS1-Ab, in healthy controls with or without COVID-19 history." (PMID 36238301, 2022). "Interestingly AABs to the vaso- and immunoregulatory receptors CXCR3, CHRM5, BDKRB1, MAS1, AGTR1, F2R/PAR-1, and STAB1 were the most significant classifiers of acute COVID-19 severity in our recent study." (PMID 36238301, 2022). "Follow-up analysis indicated that CXCR3-aab, AGTR1-aab, MAS1-aab, CHRM5-aab, and BDKRB1-aab were the five most significant predictors of COVID-19 disease-severity classification based on the number of nodes and the Gini decrease criteria for measuring variable importance." (PMID 35264564, 2022). "In the context of LOS treatment of COVID-19, ACE2 expression could depend on LOS regulated MAS1." (PMID 34937861, 2021).
Hypertension (5 papers, 2014 to 2022). The presence of chronic increased pressure in the systemic arterial system. "In addition, maternal melatonin therapy elicits longstanding alterations on renal programming, including regulation of the melatonin signaling pathway and upregulation of Agtr1b and Mas1 expression in the renin-angiotensin system (RAS), to protect male offspring against programmed hypertension." (PMID 26696906, 2015).
ovarian carcinoma (3 papers, 2019 to 2022). A malignant neoplasm originating from the surface ovarian epithelium. "These saRNA molecules were delivered into human ovarian cancer A2780 cells using the commercial vector Lipofectamine to evaluate their potential effects on MAS1 expression." (PMID 35712764, 2022). "The ACE2/MAS1 axis is involved in the complex regulation of ovarian cancer function." (PMID 34868310, 2021). "In all tested ovarian cancer cell lines (A2780, JHOM2B, SKOV‐3, and OVCA429), MAS1 RNA expression was enhanced when the three identified saRNAs (saMAS1+1514, saMAS1+1669, and saMAS1+1982) were, respectively, delivered by AD." (PMID 35712764, 2022).
breast carcinoma (2 papers, 2020 to 2022). "Compared to the untreated and non‐target (NC) controls, all three MAS1 saRNAs delivered by AD significantly enhanced the MAS1 protein and transcript levels in both breast cancer cell lines." (PMID 35712764, 2022).
colitis (2 papers, 2016 to 2021). Inflammation of the colon. "We show for the first time that the expression of ACE2/Ang 1-7/MAS-1 R are modulated post colitis induction." (PMID 26963721, 2016). "Regarding the influence of the ACE2/Ang 1-7/MAS-1 R axis in modulating colitis severity, one report demonstrated that administration to mice of GL1001 (as a chemical inhibitor of ACE2) reduced colitis severity." (PMID 26963721, 2016).
colon cancer (2 papers, 2021 to 2025). "BLACAT2 is upregulated in bladder cancer 45, gastric cancer 46, and colon cancer 47 and negatively mediates the expression of AGTR1 and MAS1." (PMID 34671200, 2021).
dementia (2 papers, 2024 to 2025). Loss of intellectual abilities interfering with an individual's social and occupational functions. "The positive correlation between IGFBP‐2 and MAS‐1 expression is noteworthy, as higher IGFBP‐2 has been correlated with increased all‐cause mortality risk in multiple human aging cohorts and predicts an increased rate of incident AD and dementia." (PMID 40264357, 2025).
Alzheimer disease (1 paper, 2025). A progressive, neurodegenerative disease characterized by loss of function and death of nerve cells in several areas of the brain leading to loss of cognitive function such as memory and language. "In the process of normal aging, heightened signaling from ACE1/AGTR1 expression is predominantly countered by ACE1/AGTR2 expression, while the levels of ACE2, MAS1, and LNPEP remain constant, while in the later stages of Alzheimer’s disease, a decline in MAS1 expression emerges." (PMID 41303587, 2025).
Anxiety (1 paper, 2025). Intense feelings of nervousness, tension, or panic often arise in response to interpersonal stresses. "Knockout of the gene MAS1 in 129P2/OlaHsd mouse cells, suggests an increase in anxiety." (PMID 40560842, 2025).
aortic valve disease (1 paper, 2018). "Expressions of genes in the renin-angiotensin system, especially CTSA, LNPEP, and MAS1, in the left atrium in MR patients significantly differed from expressions of these genes in aortic valve disease patients and normal controls." (PMID 30581499, 2018). "In the current study, MAS1 expression in the left atrium was significantly upregulated in the MR patients in comparison with aortic valve disease patients and normal controls." (PMID 30581499, 2018). "In contrast, the aortic valve disease patients with HF had significantly upregulated expression of MAS1 (fold change: 292.81, upregulation) in the left atrium compared to normal controls." (PMID 30581499, 2018). "Expressions of genes in the renin-angiotensin system, especially CTSA, LNPEP, and MAS1, in the left atrium in MR patients significantly differed from those in aortic valve disease patients and normal controls, and the differences were independent of circulating angiotensin II levels." (PMID 30581499, 2018). "Additionally, in comparison with aortic valve disease patients, MR patients had significantly downregulated CTSA and LNPEP expression and significantly upregulated MAS1 expression in the left atrium." (PMID 30581499, 2018).
asthma (1 paper, 2019). "The development of stable long acting MAS1 agonists may be a more effective alternative to EGFR inhibitors as potential anti-inflammatory therapy for asthma and other diseases." (PMID 31675376, 2019).
coagulopathies (1 paper, 2023). "The upregulation of the MAS1 circuit is related to the normal vascular system functioning, and the activation of this axis may result from a vasoprotective response of the glycoproteins, such as GPVI and vWF, involved in thromboembolism, thromboinflammation, and other coagulopathies." (PMID 38414974, 2023).
colorectal cancer (1 paper, 2021). A primary or metastatic malignant neoplasm that affects the colon or rectum. "AGTR2 was a risk factor in follicular lymphoma and colorectal cancer, whereas MAS1 was a protective factor in most tumors." (PMID 34671200, 2021).
coronary heart disease (1 paper, 2024). "The results of the study showed that SNPs of eNOS, HSP70, FKBP5, miR-146a, ACE2, MAS1, SGK1, IL-4–589, IL-6–174, TNF-α–308, CRP–717, 5-HTTLPR, and BDNF genes are associated with the comorbidity of coronary heart disease and depression." (PMID 38745947, 2024).
endothelial dysfunction (1 paper, 2024). In vascular diseases, endothelial dysfunction is a systemic pathological state of the endothelium (the inner lining of blood vessels) and can be broadly defined as an imbalance between vasodilating and vasoconstricting substances produced by (or acting on) the endothelium. "Our results demonstrate that CPE prevents endothelial dysfunction by normalizing the vasoactive/vasoconstrictive state in the kidney, modulating the expression of AT1R and AT2R/Mas1 and allowing for NO production." (PMID 39195453, 2024). "CPE also prevents the downregulation of the Mas1/AKT1/eNOS pathway, enhancing the vasorelaxant effect through NO production and avoiding endothelial dysfunction in arteriole in the remanent functional kidney." (PMID 39195453, 2024).
glioblastoma (1 paper, 2024). The most malignant astrocytic tumor (WHO grade IV). "Both ACE2 and MAS1 were significantly lower in expression in glioblastomas compared to low-grade gliomas and were decreased in glioblastomas compared to other tumour types." (PMID 38607073, 2024).
Impaired glucose tolerance (1 paper, 2024). An abnormal resistance to glucose, i.e., a reduction in the ability to maintain glucose levels in the blood stream within normal limits following oral or intravenous administration of glucose. "Mas1 is also implicated in metabolic disorders, and a knockout mouse model displays impaired glucose tolerance and increased body weight." (PMID 38909264, 2024).
Insulin resistance (1 paper, 2022). Increased resistance towards insulin, that is, diminished effectiveness of insulin in reducing blood glucose levels. "Interestingly, compared with the WT + WT BAT control mice, the WT + Mas1-/--BAT mice showed greatly impaired HFD-induced insulin resistance." (PMID 35014608, 2022).
mastitis (1 paper, 2024). Inflammation of breast tissue during lactation or postpartum due to an obstructed duct or infection. "In this investigation, LPS was employed to establish an inflammatory injury model of EpH4 EV cells to elucidate the advantageous function of Mas1 in ameliorating mastitis." (PMID 39071779, 2024). "This study clarified the role of Mas1 in mastitis, which could provide important targets for immunotherapy and drug development of cow mastitis." (PMID 39071779, 2024). "LPS treatment of EpH4 EV cells led to a significant downregulation of Mas1 transcript levels, which attracted our great interest, suggesting that Mas1 may be an important target for the treatment of mastitis." (PMID 39071779, 2024). "However, the role of Mas1 in mastitis remains to be elucidated." (PMID 39071779, 2024).
metabolic syndrome (1 paper, 2010). A cluster of metabolic risk factors for CARDIOVASCULAR DISEASES and TYPE 2 DIABETES MELLITUS. "Mas1 is a G-protein coupled receptor recently identified as playing a central role in lipid metabolism and metabolic syndrome." (PMID 21092094, 2010).
Obesity (1 paper, 2012). Accumulation of substantial excess body fat. "The results of the logistic regression further show that an increased number of risk alleles correlates with a significantly increased risk of obesity, in comparison with the genotype combinations of MAS1 rs220721 GG and BDKRB2 rs1799722 CC." (PMID 22880127, 2012). "Our findings, for the first time, suggested that the interaction between MAS1 and BDKRB2 conferred the genetic susceptibility to obesity in the Chinese population." (PMID 22880127, 2012). "Two genetic variants in MAS1 and BDKRB2 were identified to be significantly associated with obesity risk." (PMID 22880127, 2012). "In conclusion, our study is the first to show evidence that the interaction between MAS1 and BDKRB2 is associated with the predisposition of obesity in our Chinese population." (PMID 22880127, 2012). "In this research, differences were observed in the distribution of polymorphic variants of MAS1 and BDKRB2 between obesity patients and controls." (PMID 22880127, 2012). "Moreover, the combination of the MAS1 rs220721 and the BDKRB2 rs1799722 was associated with a significantly increased risk of obesity (OR 1.82, CI 95%: 1.15–2.88, p = 0.0103)." (PMID 22880127, 2012). "In our study, GMDR suggested that the combination between MAS1 rs220721 and BDKRB2 rs1799722 was the best model, irrespective of whether a dichotomous (obesity) or continuous (BMI) variable was measured, adjusting for the covariates." (PMID 22880127, 2012).
osteosarcoma (1 paper, 2018). A usually aggressive malignant bone-forming mesenchymal neoplasm, predominantly affecting adolescents and young adults. "Similarly, human osteosarcoma cell lines U-2 OS and MNNG-HOS with MAS1 knockdown showed increased proliferation activity as compared to osteosarcoma cells non-treated siRNA5." (PMID 30361641, 2018).
pancreatic cancer (1 paper, 2022). "Further, a significant increase in MAS1 protein was detected in all tested pancreatic cancer cell lines (AsPC1, CFPAC1, and PANC1) after saMAS1+1982/AD treatment." (PMID 35712764, 2022).
tuberculosis (1 paper, 2023). A chronic, recurrent infection caused by the bacterium Mycobacterium tuberculosis. "Second, while expression levels of SAS-1 and IMM-AGE declined and those of MAS-1 increased with age, levels in older persons approximated those of younger individuals with conditions associated with lower immunocompetence and inflammation (e.g., tuberculosis, HIV)." (PMID 37311745, 2023).
cancer (8 papers, 2010 to 2022). A tumor composed of atypical neoplastic, often pleomorphic cells that invade other tissues. "Together, these data suggest that upregulation of MAS1 expression by saMAS1 effectively inhibits cancer cell migration." (PMID 35712764, 2022). "In this study, we demonstrate that MAS1 saRNAs (saMAS1) delivered by AD consistently enhanced the expression of MAS1 in the RAS system in multiple cancer cell lines and models." (PMID 35712764, 2022). "The increase in MAS1 expression resulted in effective inhibition of cancer cell migration and had a potent anticancer effect, leading to significant suppression of tumorigenesis in xenograft models and reduced growth of patient tumor‐derived organoids." (PMID 35712764, 2022). "Our studies demonstrate that saRNA‐mediated increase of MAS1 expression is an effective approach to inhibit cancer proliferation in patient‐derived tumor models and should have broad relevance in cancer treatment." (PMID 35712764, 2022). "Our study therefore highlights the tremendous potential of using and leveraging saRNAs to address complex target such as MAS1 as novel therapy for the management of cancers, which currently have limited treatment options." (PMID 35712764, 2022). "From the RAS pathway, possible receptors are AGTR2 and MAS1 that have opposing effects to that of AGTR1 in several cancers." (PMID 30845964, 2019). "Small activating RNAs (saRNAs) targeting MAS1, delivered by an amphiphilic dendrimer (AD) vector, enhance MAS1 expression and counteract the angiotensin II pathway in cancer cells, leading to significantly suppressed tumorigenesis and inhibited tumor progression." (PMID 35712764, 2022). "AGTR2 and MAS1 were weakly expressed in normal and tumor tissues as well as cancer cell lines." (PMID 34671200, 2021). "Mas1 was first described as an oncogene and continues to be of interest in cancer." (PMID 32324784, 2020). "Taken together, our data offer molecular evidence that the increase in MAS1 expression is able to suppress the AGTR1‐mediated SRE activity and the calcium response via formation of receptor heterocomplexes in cancer cells." (PMID 35712764, 2022). "Our results indicate that the saRNA‐enhanced MAS1 expression counteracts the Ang II/AGTR1 axis via both ligand‐dependent and ‐independent mechanisms, and is beneficial to suppress cancer development in animal models." (PMID 35712764, 2022). "Specifically, saRNAs promoting the expression of Mas receptor (MAS1), a GPCR that counteracts the classical angiotensin II pathway in cancer cell proliferation and migration, are identified." (PMID 35712764, 2022). "The oncoprint displayed an overall alteration frequency of RAS family of 15.2% in TCGA pan-cancer across TCGA cancers, with the highest frequency existing for ACE (4%), followed by AGT (3%), AGTR1 (3%), ACE2 (2.3%), AGTR2 (1.5%) and MAS1 (1.4%)." (PMID 34671200, 2021). "In tumor tissue, AGTR2 and MAS1 were weakly expressed; in contrast, ACE and AGT presented broad expression across 33 cancer types." (PMID 34671200, 2021). "In this study, we comprehensively integrated and analyzed the molecular characteristics of 6 significant members of the RAS family across pan-cancer: AGT, ACE, ACE2, AGTR1, AGTR2, and MAS1." (PMID 34671200, 2021). "It has been described that the ACE2/Ang1-7/MAS1 cascade opposes the effects of the ACE1/Ang II/AT1 receptor axis, inhibiting cancer cell proliferation, reducing the migratory potential and invasiveness, limiting the formation of new blood vessels." (PMID 32604999, 2020). "This likely results from activation of MAS1 and the inhibition of AGTR1, reducing survival and growth of the spheroids as well as cancer metastasis." (PMID 30845964, 2019). "MAS1, is the first GPCR to be reported to have any relation to cancer development." (PMID 22715397, 2012).
MAS1 also shares sentences with these, for which no sentence is quoted: infection (8 papers); Sepsis (5); tumor (5); abscess (4); endocarditis (4); cardiac hypertrophy (2); infective endocarditis (2); metabolic disease (2); prostate carcinoma (2); Arthritis (1); atherosclerosis (1); Autoimmunity (1); bacteremia (1); bladder cancer (1); Bovine mastitis (1); cardiac disease (1); cardiovascular disease (1); cavernous hemangioma (1); depression (1); Ecchymosis (1); fatty liver disease (1); follicular lymphoma (1); gastric cancer (1); glioma (1); hospital-acquired infections (1); hypertrophy (1); ischemia (1); Liver abscess (1); liver cancer (1); liver failure (1).
A further 14 diseases each share a sentence with MAS1 in 1 paper.